ENSG00000258830 (novel protein)
Gene: Protein-coding gene on chromosome 12 (57,249,609 to 57,296,484, reverse strand). Ensembl gene ENSG00000258830.
Genetic constraint (gnomAD): Missense variants: 48 observed, 67.18 expected, observed/expected ratio (o/e) 0.71, 90% interval 0.57 to 0.91. Synonymous variants: 18 observed, 20.02 expected, observed/expected ratio (o/e) 0.9, 90% interval 0.62 to 1.33.